Y_RNA (Y RNA )
Gene: Miscellaneous RNA gene on chromosome 4 (56,818,218 to 56,818,314, reverse strand). Ensembl gene ENSG00000251799.
Homologues: Orthologues: chimpanzee Y_RNA (98% identical). Paralogues in human: Y_RNA (89% identical), Y_RNA (88% identical), RNY3 (87% identical), Y_RNA (87% identical), RNY3P1 (86% identical), Y_RNA (86% identical), Y_RNA (85% identical), Y_RNA (84% identical), RNY3P10 (82% identical), RNY3P14 (82% identical), RNY3P16 (82% identical), Y_RNA (82% identical), and 96 more.